SQSTM1 (sequestosome 1)
Diseases named in the same sentence as SQSTM1 in open-access papers (continued):
Sharing a sentence is not in itself a finding about the gene and the disease.
SQSTM1 also shares sentences with these, for which no sentence is quoted: inclusion body myositis (4 papers); multiple myeloma (4); sarcoma (4); disorders of iron metabolism (3); memory impairment (3); non-alcoholic steatohepatitis (3); cerebellar ataxia (2); cholangiocarcinoma (2); cognitive decline (2); inflammatory bowel disease (2); inflammatory myofibroblastic tumor (2); intrahepatic cholangiocarcinoma (2); ischemic stroke (2); Lewy body dementia (2); metabolic diseases (2); neuropathies (2); scrapie (2); age-related macular degeneration (1); alopecia areata (1); atopic dermatitis (1); autoimmune disease (1); Behavioral Variant Frontotemporal Dementia (1); bladder urothelial carcinoma (1); brain diseases (1); breast (1); breast invasive carcinoma (1); buccal mucosa squamous cell carcinoma (1); cardiovascular diseases (1); Charcot-Marie-Tooth disease type 1A (1); Charcot-Marie-Tooth disease type 4 (1).
A further 74 diseases each share a sentence with SQSTM1 in 1 paper.